AKR1C4 (aldo-keto reductase family 1 member C4)
Description:
Cytosolic aldo-keto reductase that catalyzes NADPH-dependent reduction of ketosteroids to hydroxysteroids. Displays broad substrate specificity with distinct positional and stereochemistry, primarily generating 3alpha/beta-, 17beta- and 20alpha-hydroxysteroids. Required for male sex determination as a component of the 'backdoor' androgen biosynthesis pathway that generates 5alpha-dihydrotestosterone (5alpha-DHT) via pregnanes. Acts together with AKR1C2 to convert 5alpha-dihydroprogesterone (5alpha-DHP) to 3alpha-hydroxy-5alpha-pregnan-20-one (3alpha,5alpha-THP/allopregnanolone), leading to 5alpha-DHT secretion necessary for embryonic gonad differentiation into testis. May regulate the concentrations of circulating neurosteroids. Reduces 5alpha-dihydroprogesterone (5-alpha-DHP) and 5alpha-dihydrodeoxycorticosterone (5-alpha-DHDOC) precursors to 3alpha-hydroxy-5alpha-pregnan-20-one (3alpha,5alpha-THP/allopregnanolone) and 3alpha,21-dihydroxy-5alpha-pregnane-20-one (3alpha,5alpha-THDOC) neuroactive steroids known to alter neural excitability via allosteric activation of gamma-aminobutyric acid type A receptors (GABAAR). Regulates ligand availability for steroid hormone receptors. Catalyzes the inactivation of 5alpha-DHT and progesterone converting them into 3alpha/beta-androstanediols and (20S)-hydroxypregn-4-en-3-one, respectively. May contribute to the metabolism of adrenal-derived androgens via reduction of 11-keto-5alpha-androstane-3,17-dione (11K-Adione) into 11-ketoandrosterone (11KAST) and of 11-ketodihydrotestosterone (11KDHT) into 11-keto-5alpha-androstane-3alpha/beta,17beta-diol (11K-A3diol). Catalyzes the reduction of estrone into 17beta-estradiol but with low efficiency. In androgen catabolism, may predominantly act as a phase I enzyme by introducing a hydroxyl group prior to conjugation. It can nevertheless participate in the alternative phase II pathway by directly reducing sulfate- or glucuronide-conjugated androgens. Catalyzes the biotransformation of the pesticide chlordecone (kepone) to its corresponding alcohol, leading to increased biliary excretion of the pesticide and concomitant reduction of its neurotoxicity since bile is the major excretory route. In vitro can efficiently catalyze bidirectional conversion between ketosteroids and hydroxysteroids using NADPH/NADP(+) or NADH/NAD(+) as cofactors. In vivo however, the reductase activity prevails since the major reducing cofactor NADPH inhibits NAD(+)-dependent oxidase activity.
Synonyms: CDR; DD-4; DD4; CHDR; HAKRA; C11; 3-alpha-HSD; MGC22581
Tractability: Small molecule: a structure with a bound ligand is known; a high-quality ligand is known; it has a high-quality binding pocket. PROTAC: ubiquitination databases record sites on it; its protein half-life has been measured; a small molecule that binds it is known.
Target class: Enzyme; Oxidoreductase
Gene: Protein-coding gene on chromosome 10 (5,195,462 to 5,220,608, forward strand). Ensembl gene ENSG00000198610.
Subcellular location: Cytoplasm, cytosol
Subcellular location (Human Protein Atlas): Cytosol; Nucleoplasm; Endoplasmic reticulum; Nucleoli fibrillar center
Pathways (Reactome):
Metabolism: Synthesis of bile acids and bile salts via 24-hydroxycholesterol; Synthesis of bile acids and bile salts via 27-hydroxycholesterol; Synthesis of bile acids and bile salts via 7alpha-hydroxycholesterol
Sensory Perception: Retinoid metabolism and transport
Gene Ontology:
Molecular function: 3-alpha-hydroxysteroid 3-dehydrogenase [NAD(P)+] activity; 5-alpha-androstane-3-beta,17-beta-diol dehydrogenase (NADP+) activity; androsterone dehydrogenase [NAD(P)+] activity; chlordecone reductase activity; estradiol 17-beta-dehydrogenase [NAD(P)+] activity; oxidoreductase activity, acting on NAD(P)H, quinone or similar compound as acceptor; protein binding; retinal dehydrogenase (NAD+) activity; testosterone dehydrogenase (NAD+) activity; testosterone dehydrogenase (NADP+) activity; alcohol dehydrogenase (NADP+) activity; aldose reductase (NADPH) activity; bile acid binding; bile acid transmembrane transporter activity; electron transfer activity; ketosteroid monooxygenase activity; 17-beta-hydroxysteroid dehydrogenase (NAD+) activity; 3-beta-hydroxysteroid 3-dehydrogenase (NADP+) activity; androstan-3-alpha,17-beta-diol dehydrogenase (NAD+) activity; oxidoreductase activity
Biological process: cellular response to jasmonic acid stimulus; daunorubicin metabolic process; doxorubicin metabolic process; androgen metabolic process; bile acid and bile salt transport; bile acid biosynthetic process; progesterone metabolic process; prostaglandin metabolic process; retinoid metabolic process; steroid metabolic process; hormone metabolic process; monocarboxylic acid metabolic process
Cellular component: extracellular exosome; cytoplasm; cytosol
Genetic constraint (gnomAD): Loss-of-function variants: 36 observed, 35.55 expected, observed/expected ratio (o/e) 1.01, 90% interval 0.77 to 1.34. The upper end of that interval is the gene's LOEUF score, 1.34, which puts it in group 5 of 6, group 1 being the genes least tolerant of losing a copy. Missense variants: 374 observed, 350.84 expected, observed/expected ratio (o/e) 1.07, 90% interval 0.98 to 1.16. Synonymous variants: 145 observed, 128.99 expected, observed/expected ratio (o/e) 1.12, 90% interval 0.98 to 1.29.
Homologues: Orthologues: chimpanzee AKR1C4 (98% identical), zebrafish akr1a1a (41% identical), zebrafish zgc:56622 (39% identical), Caenorhabditis elegans Y39G8B.1 (38% identical), Drosophila melanogaster CG6083 (37% identical), Caenorhabditis elegans C07D8.6 (37% identical), Caenorhabditis elegans Y39G8B.2 (33% identical), zebrafish zgc:110366 (31% identical), Caenorhabditis elegans F53F1.2 (31% identical), zebrafish zgc:101765 (30% identical), tropical clawed frog XB5731323 (30% identical), tropical clawed frog XB5994047 (30% identical), and 9 more. Paralogues in human: AKR1C3 (84% identical), AKR1C1 (83% identical), AKR1C2 (81% identical), AKR1C8 (67% identical), AKR1D1 (57% identical), AKR1B1 (48% identical), AKR1B10 (48% identical), AKR1B15 (46% identical), AKR1E2 (44% identical), AKR1A1 (42% identical), KCNAB3 (27% identical), KCNAB2 (26% identical), and 4 more.
Diseases named in the same sentence as AKR1C4 in open-access papers:
AKR1C4 is named in the same sentence as 20 diseases in open-access papers, as found by Europe PMC text mining. Sharing a sentence is not in itself a finding about the gene and the disease. The quoted sentences say what the papers report.
prostate carcinoma (2 papers, 2021 to 2022). A carcinoma that arises from epithelial cells of the prostate gland. "Patients with positive family history for prostate cancer showed high levels of EGFR, TG, TC, LDL, alkaline phosphatase (ALP), but low AKR1C4, SLDLRP1, CAV1 and ABCA-1 levels." (PMID 36480560, 2022).
colorectal carcinoma (1 paper, 2022). A malignant epithelial neoplasm that arises from the colon or rectum and invades through the muscularis mucosa into the submucosa. "As an important member of the AKR1C family, AKR1C4 expression was found to be elevated in colorectal carcinoma and lung cancer; however, there is no known study illustrating the prognostic value of AKR1C4 in NPC patients." (PMID 35953777, 2022).
gallstones (1 paper, 2023). Solid crystalline precipitates in the biliary tract, usually formed in the gallbladder, resulting in the condition of cholelithiasis. "The downregulation of AKR1C4 and AKR1D1, which are involved in the synthesis of bile acids and bile salts that enhance cholesterol solubility, may promote gallstone formation." (PMID 38111640, 2023).
glioma (1 paper, 2023). A benign or malignant brain and spinal cord tumor that arises from glial cells (astrocytes, oligodendrocytes, ependymal cells). "Several aldo-keto reductases are responsible for the metabolization of oxcarbazepine (AKR1C1, AKR1C2, AKR1C3, and AKR1C4), which have not been found to be expressed in the brain or in gliomas." (PMID 37190109, 2023). "Since the enzymes responsible for the metabolization of oxcarbazepine (AKR1C1, AKR1C2, AKR1C3, and AKR1C4) are highly expressed in hepatocytes but not in glioma cells, we expect only marginal transformation to MHD in our in vitro proliferation assay." (PMID 37190109, 2023).
Insulin resistance (1 paper, 2019). Increased resistance towards insulin, that is, diminished effectiveness of insulin in reducing blood glucose levels. "Vitamin K epoxide reductase complex, subunit 1-like 1 (VKORC1L1), BTD, GPC1, MOCOS, GPC5, AKR1C4, and NMNAT2 are novel biomarkers for the development of insulin resistance." (PMID 30678306, 2019).
liver cancer (1 paper, 2022). An epithelial or non-epithelial malignant neoplasm that arises from the liver. "Other genes in this family (AKR1C1-3) have been associated with different cancers including liver cancer; however the role of AKR1C4 in liver cancer is still unclear as expression level difference between tumor and normal tissue were found to be inconsistent across different databases." (PMID 36503519, 2022). "It is possible that introgression is impacting AKR1C4 expression in liver cancer." (PMID 36503519, 2022). "Consistent with this, we find higher expression of AKR1C4 in liver cancer patients with Neanderthal introgression compared to liver cancer patients without Neanderthal introgression in this gene, suggesting introgression may be affecting expression at AKR1C4 in liver cancer." (PMID 36503519, 2022).
lung adenocarcinoma (1 paper, 2021). A carcinoma that arises from the lung and is characterized by the presence of malignant glandular epithelial cells. "The expression of AKR1C1, AKR1C2, AKR1C3, and AKR1C4 proteins, which was mainly overexpressed in lung adenocarcinoma (A549) cells and associated with drug resistance in NSCLC, was found in the A549 CD166 + EpCAM + CSC subpopulation." (PMID 33670440, 2021).
prostate adenocarcinoma (1 paper, 2022). "It was demonstrated via a microarray analysis of prostate adenocarcinoma that AKR1C4 gene was altered in 25% of metastatic CRPC cases." (PMID 36480560, 2022).
prostate tumors (1 paper, 2023). "The Aldo-Keto reductase family members (AKR1C1, AKR1C3, AKR1C4, and AKR1C8P) AKR1C1 and AKR1C3 were among the highest upregulated genes in our OC2 network, and their expression increases with disease progression in prostate tumors (left)." (PMID 37484909, 2023).
cancer (5 papers, 2013 to 2022). A tumor composed of atypical neoplastic, often pleomorphic cells that invade other tissues. "High-risk genes in the model, including GPX3, AKR1C4, SPHK1and ADCY5, have been reported to promote hypermethylation, rare mutations, cancer progression, poor prognosis, and the developmental process of malignant cells in CRC patient samples or cell lines." (PMID 32953273, 2020). "Despite being expressed specifically in the liver and stomach, AKR1C4 has been proposed as a possible target for cancer therapy in these tumours." (PMID 29304754, 2018).
AKR1C4 also shares sentences with these, for which no sentence is quoted: tumor (5 papers); breast carcinoma (2); esophageal cancer (1); liver fibrosis (1); lung carcinoma (1); osteosarcoma (1); rectum adenocarcinoma (1); stomach adenocarcinoma (1); thyroid carcinoma (1); uterine corpus endometrial carcinoma (1).